ACLY (ATP citrate lyase)
Diseases named in the same sentence as ACLY in open-access papers (continued):
Sharing a sentence is not in itself a finding about the gene and the disease.
tumor (continued). "The protein stability of ATP-citrate lyase (ACLY) and fatty acid synthase (FASN) is controlled through the dynamic processes of acetylation and deacetylation, thereby regulating de novo lipogenesis and tumor growth." (PMID 39551780, 2024). "Finally, we investigated the tumour‐promoting effect and molecular mechanism of Sirtuin 2 (SIRT2)‐mediated ACLY deacetylation in ESCC." (PMID 38426936, 2024). "Among them, as typical representatives, ATP citrate lyase (ACLY) is highly expressed in the adipose tissue and liver, and oxoglutarate dehydrogenase-like (OGDHL) exhibits a tumor suppressor effect in HCC, which is consistent with the results of our preliminary exploration." (PMID 38282028, 2024). "In addition, we further investigated the effects of BMS‐303141 on the expressions of lipid synthesis‐related proteins including SREBF1, MOGAT2, FASN, ACC1, ACS and ACLY in ESCC cells and xenografted tumour tissues by Western blot." (PMID 38426936, 2024). "In summary, these findings suggest that inhibition of ACLY could increase immune infiltration in CCA, highlighting its potential role in modulating the tumor microenvironment." (PMID 39399493, 2024). "In NSCLC, the stability and activation of ACLY are enhanced by the dissociation between E3 ligase NEDD4 and ACLY, which promotes a high level of acetyl-CoA and fatty metabolism, subsequently inducing tumor proliferation." (PMID 37176148, 2023). "The inhibitors of ACLY, including SB-204990 and ETC1002, have shown the latent anti-tumor effects." (PMID 37122003, 2023). "Like ACLY, enforced expression of ACSS2 in T cells increased acetate-derived carbon incorporation in citrate and fatty acid, whereas reducing ACSS expression in T cells impairs IFN-γ production by tumor-infiltrating lymphocytes and tumor clearance." (PMID 38060103, 2023). "The combined pharmacological inhibition of ACLY and PLK1 may inhibit pan-tumor cell proliferation through UBE2C to achieve a “triple win”." (PMID 37958642, 2023). "ACLY was increased in the tumor tissues compared with non-tumorous tissues and upregulated at stage B/C." (PMID 37122003, 2023). "Since ACLY is the key regulator between the high rates of aerobic glycolysis and DNL, which is exhibited in many types of tumor cells, it is possible that bempedoic acid may influence the changes in DNL pathway molecules." (PMID 37958642, 2023). "Consistently, the higher expression level of indispensable genes for DNL, including ATP citrate lyase (ACLY), acetyl-CoA carboxylase alpha (ACACA), and fatty acid synthase (FASN) were observed in tumor tissue, further corroborating the pronounced DNL during hepatocarcinogenesis." (PMID 35406630, 2022). "Indeed, tumor cells often overexpress acetyl-CoA carboxylase (ACACA), ATP citrate lyase (ACLY), and fatty acid synthase (FASN), key enzymes responsible for de novo biosynthesis of fatty acids, which makes them attractive targets for therapeutic interventions." (PMID 34206240, 2021). "In addition, we validated (i) the co-regulatory feedback loop between SREBF1/TP63/KLF5, and (ii) canonical target genes of SREBF1 in fatty-acid metabolism (e.g., ACLY, FASN, and SCD) in xenograft tumor samples." (PMID 34272396, 2021). "Recent examples include knockdown of ACLY impairing pancreatic tumor formation and knockdown of FASN blocking tumor development in mTOR-driven liver cancer, while pharmacological inhibition of FAS reduced tumor growth in preclinical models of castration-resistant prostate cancer." (PMID 33413672, 2021). "Interestingly both FASN and ACLY were significantly upregulated in the four BCa patients’ datasets that we interrogated and the expression of FASN positively correlated with tumor aggressiveness, advanced grade and stage, and poor prognosis." (PMID 34764423, 2021).
tumor (continued). "As ACLY, ACC, and FASN are frequently upregulated in tumor cells and their inhibition reduces tumor growth, it is widely recognized that the increased capacity for producing lipids de novo is a crucial determinant for the tumor progression." (PMID 32266157, 2020). "Indeed, ACLY-dependent metabolism is elevated during PDAC development, and deletion of ACLY suppressed tumor growth." (PMID 31569510, 2019). "Additionally, UBR4 promotes ubiquitination of ATP-citrate lyase (ACLY), a key regulator of fatty acid biogenesis, suggesting that UBR4 has a role in tumor progression and lipid synthesis." (PMID 30157281, 2018). "Our work also suggests that α2M*/CS-GRP78 signaling modulates the rate of acetyl-CoA generation by salvage pathways independent of ACLY which can be sufficient to maintain macromolecular synthesis that supports tumor growth." (PMID 29296215, 2017). "Third, the α2M*/CS-GRP78 mediated AKT activation regulates ACLY and ACSS1 expression which might plays a critical role in integrating cellular metabolism with signal transduction to drive tumor growth in response to environmental constraints." (PMID 29296215, 2017). "Protein levels of USP13, ACLY and OGDH were simultaneously reduced in the Dox-treated tumours." (PMID 27892457, 2016). "Importantly, this showed that the regulation between ACC1/ACLY and ETV4 was relevant in tumor expression datasets." (PMID 26452058, 2015). "Hence, citrate quits the mitochondria to give via ATP citrate lyase, acetyl CoA and OAA in the cytosol of tumor cells." (PMID 21649891, 2011). "In addition, in mice with tumor formation in situ, the tumor bodies of the group with high expression of PPARG also had higher expression levels of genes related to fatty acid metabolism, such as ACACA, ACLY and ACSS2 and so on." (PMID 40303293, 2025). "The differential expression of ATP citrate lyase (ACLY), acetyl-CoA carboxylase alpha (ACACA), fatty acid synthase (FASN), SCD, and SREBF1 was further validated via RT‒qPCR subsequent to magnetic-based cell sorting of co-cultured H2228 and H3122 tumor spheroids." (PMID 40524253, 2025). "In addition, ACLY K468-Ac level was upregulated in HCC tumor tissues compared with their non-tumorous counterparts." (PMID 39085201, 2024). "However, the relevance of ACLY expression levels in somatic tissues (i.e., non‐tumor) in humans has not been investigated in depth." (PMID 38760909, 2024). "Modulating the expression of ACLY and FASN through SREBP1 affects de novo lipogenesis production in PRAD cells, promoting cell proliferation, which is consistent with the inhibitory effects observed upon ACLY knockdown in NPC and PRAD that inhibit tumor cell migration and growth." (PMID 38189049, 2023). "Tumor cells undergo lipid metabolic reprogramming through de novo lipogenesis involving key transcription factors such as sterol regulatory element binding protein (SREBP), ATP citrate lyase (ACLY), acetyl-CoA carboxylase (ACC), fatty acid synthase (FASN) and stearoyl-CoA desaturase 1 (SCD1)." (PMID 38189049, 2023). "However, aside from FASN, other enzymes involved in de novo FA synthesis also play an instrumental part in tumour progression, such as ACC, the rate-limiting enzyme for de novo FA synthesis, and ACLY, which provides glucose-derived acetyl-CoA as the main substrate for both ACC and FASN." (PMID 35448537, 2022). "In addition, inhibition of ACLY activity by specific inhibitor SB204990 induced increased levels of intracellular CA in both tumor cells and normal control cells, suggesting internal regulation of citrate by ACLY in tumor cells." (PMID 34747157, 2022).
tumor (continued). "As ACLY was not included in the annotation of fatty acid metabolism associated pathways and gene sets in GO and KEGG, we analyzed the correlation between ACLY and 20 core genes in lipid metabolism process through TIMER in TCGA tumor cohort." (PMID 34344378, 2021). "Besides, immunochemistry analysis showed that ACLY expression was evidently decreased in the tumor tissues of IGF2BP1 knockout group or NONO knockout group, compared to that in control group." (PMID 32884448, 2020). "On the contrary, the expression of ACLY did not change at 5 and 10 mM citrate; at 1 mM, it even increased as compared to the control, thus suggesting that, in non-tumor cells, changes of acetylated histone level do not correspond to a change of ACLY expression, as instead shown by HepG2 cells." (PMID 33282912, 2020). "PKM2, SCD1, ACAC, and ACLY proteins were upregulated regardless of tumor differentiation grade." (PMID 25948777, 2015). "Overall, as the first study observing the effect of ACLY gene polymorphisms on CRC prognosis in a Chinese population, our results strongly suggest that 2 SNPs of ACLY genes may be independent prognostic markers for recurrence and survival prediction in CRC patients with advanced stage tumor." (PMID 25890184, 2015). "ACLY and ME expression may therefore be altered in malignant tumor cells compared to non-neoplastic tissues." (PMID 25962060, 2015). "Thus, the absence of ACLY exon 14 alone is not sufficient to alter tumor phenotypes." (PMID 38815867, 2024). "In addition, ACLY expression was associated with HCC metastasis and tumour‐node‐metastases staging." (PMID 33393219, 2021). "The largest number of changes in gene expression (n = 8) between tumour and non-malignant groups were identified in metabolic genes (PFKL, ATP5A1, UQCRFS1, CPT2, COX5A, ACLY, GPD2, and G6PD)." (PMID 36142793, 2022). "Similarly, while the expression levels of ACLY, FASN, ACSL1, and ACSL5 in the liver tissues were decreased in C26 tumor-bearing mice compared with control mice without tumors, their expression levels were significantly increased in the liver tissues of the mice fed with a fenofibrate diet." (PMID 38245529, 2024). "In addition, SCT treatment could upregulate ACLY gene expression but did not affect citrate synthesis (CS) or mitochondrial citrate carrier SLC25A1 expression in MCF7 and HCT116 tumor cells." (PMID 34747157, 2022). "Considering the strong demand for acetyl-CoA in tumor cells but not for OAA, the administration of citrate at a high concentration to HepG2 cells determines an accumulation of OAA, which reduces the further synthesis of OAA and acetyl-CoA and therefore ACLY expression." (PMID 33282912, 2020).
infection (19 papers, 2015 to 2025). The state of being infected such as from the introduction of a foreign agent such as serum, vaccine, antigenic substance or organism. "To get a more precise picture of how ACLY inhibition is affecting VACVreplication, we added SB-204990 at different times post-infection [0 (at thetime of infection), 1, 2, and 3 hpi] and measured E3 protein levels at 4 hpi." (PMID 39475274, 2024). "This infection enhances ACLY S455phosphorylation and lipid droplet formation, with evidence suggesting dependency onVGF, the VACV homolog of cellular EGF." (PMID 39475274, 2024). "Next, we investigated the role of the VACV VGF-EGFR-Akt-ACLY signaling axis ininducing lipid droplets upon infection." (PMID 39475274, 2024). "Three genes involved in the synthesis of acetyl CoA, AACS (2.0 fold), ACAT2 (3.5 fold) and ACLY (2.2 fold) were up-regulated by infection; however, this compound and it precursors or metabolites were largely unaltered by infection." (PMID 32732949, 2020). "Infection with vΔVGF abolishedthis upregulation of ACLY phosphorylation." (PMID 39475274, 2024). "Solanidine has been reported to inhibit pathogen infection and is produced through the mevalonate pathway from acetyl coenzyme A (acetyl-CoA), which is in the cytosol, and can also be produced by the enzyme ATP-citrate lyase from the organic acid citrate." (PMID 32471154, 2020). "In contrast to the wild type, FLAG-tagged mutant ACLY, PFAS, hnRNP K, ALIX, and p115 resistant to 3Cpro cleavage in vitro were also resistant to cleavage during infection." (PMID 29437971, 2018). "Remarkably, we found that VACV infection increased ACLYphosphorylation at S455 in HFFs.Moreover, we found that VACV infection increased ACLY phosphorylation wasobservable at 2- and 8 h post-infection (hpi), indicating that VACV can modulate ACLY activity startingearly during the infection." (PMID 39475274, 2024). "Notably, G6PD, ACLY, and PGK1 were also detected in our IP-MS analysis of SIRT2 interactions during infection." (PMID 37916830, 2023). "Although RIPK1 and ACLY were cleaved by 3Cpro, the masses of the in vitro cleavage products were not similar to those produced during infection." (PMID 29437971, 2018). "Notably, phosphorylation could be rescued by infection withvΔVGF_Rev, indicating that VGF is required to induce ACLY phosphorylation." (PMID 39475274, 2024). "There was no detectable decrease in the full-length ALIX, ACLY, hnRNP K, RIPK1, GBF1, and PFAS proteins, suggesting that only a subset of these target proteins are cleaved during infection." (PMID 29437971, 2018).
metabolic disease (17 papers, 2020 to 2026). A congenital disorder (due to inherited enzyme abnormality) or acquired (due to failure of a metabolically important organ) disorder resulting from an abnormal metabolic process. "Given the key function in lipid metabolism, ACLY inhibitors were formerly developed for metabolic diseases." (PMID 38755125, 2024). "Thus, the knowledge of molecular mechanism of ACLY regulation at translational level, reported in the present study, provides new elements for therapeutic treatment of metabolic diseases." (PMID 32054087, 2020). "Even though clinical trials are pursuing the inhibition of ACLY to stall lipid accumulation in metabolic disorders, evidence supports that during fructose-induced fat accumulation ACSS2-processed acetate supplies substantial lipogenic acetyl-CoA independently of ACLY." (PMID 38383863, 2024).
cardiovascular disease (11 papers, 2021 to 2025). "The method was recently implemented in a study of ACLY and cardiovascular disease which incorporated multiple germline genetic variants (IVs) to construct GS as single IV and further inferred the causal relationship between ACLY inhibitors and the reduced risk of cardiovascular disease." (PMID 33868364, 2021). "Genetic variants that mimic the effects of ATP citrate lyase inhibitors and statins appear to reduce plasma LDL cholesterol levels through the same mechanism of action, and are associated with cardiovascular disease risk for each unit of LDL cholesterol reduction." (PMID 37724687, 2023). "Genetic variants that mimic the effect of ATP citrate lyase inhibitors and statins appeared to lower plasma LDL-C levels by the same mechanism of action and were associated with similar decreased risk of cardiovascular disease per unit decrease in the LDL-C level." (PMID 36301892, 2022). "Furthermore, bempedoic acid (ETC-1002), a specific and well tolerated liver-targeting ACLY inhibitor, has been recently approved for clinical use by FDA for the treatment of cardiovascular disease." (PMID 37842307, 2023).
kidney disease (7 papers, 2021 to 2026). "This review consolidates current knowledge on ACLY in kidney diseases, highlighting its mechanistic contributions, and underscoring its significant potential for diagnostic and therapeutic innovation." (PMID 41958067, 2026). "Accumulating evidence positions ACLY not merely as a metabolic enzyme but as a key pathogenic driver in various kidney diseases." (PMID 41958067, 2026). "Healthy controls and kidney disease samples showed strong expression of DNL genes, including ACSS2, NR1H3 (liver X receptor α [LXRA]), NR1H4 (farnesoid X receptor [FXR]), SREBF1, SCAP, PLIN2, PLIN5, ACACAB, ATP citrate lyase (ACLY), and FASN in PT cells and some other tubule cells." (PMID 38051585, 2023).
cardiac diseases (2 papers, 2012 to 2023). "In agreement with the notion in cardiac dysfunction these pathways may be altered, chronic treatment with the β-agonist isoproterenol, which mimics the sympathetic overactivation observed in several cardiac diseases, increased mRNA levels for ACLY, ACC and FAS several fold." (PMID 22768193, 2012).
neurodegenerative disease (2 papers, 2022 to 2025). A disorder of the central nervous system characterized by gradual and progressive loss of neural tissue and neurologic function. "Targeting proteins such as fatty acid synthase (FASN), diacylglycerol O-acyltransferase 1 (DGAT), and ATP-citrate lyase (ACLY) has shown promise in alleviating some symptoms of neurodegenerative diseases." (PMID 41373990, 2025). "Targeting FASN, Diacylglycerol O-acyltransferase 1 (DGAT), ATP-citrate lyase (ACLY) and maybe other important proteins appears to alleviate neurodegenerative diseases to some extent." (PMID 36588702, 2022).
immune diseases (1 paper, 2021). "Thus, future investigations systematically evaluating ACLY as a drugable target for IBD and other immune diseases are in need." (PMID 34491895, 2021).
liver (1 paper, 2022). "We previously demonstrated that treatment with BemA (bempedoic acid), an inhibitor of ATP citrate lyase, significantly reduces fatty liver in a model of liver steatosis (HFHFr—female Sprague-Dawley rat fed a high-fat high-fructose diet)." (PMID 36613916, 2022).
ACLY also shares sentences with these, for which no sentence is quoted: thrombosis (65 papers); antiphospholipid syndrome (40); lupus (30); Thrombocytopenia (18); Arterial thrombosis (15); autoimmune disease (15); Stroke (15); Hypertension (8); hypercoagulability (6); migraine (5); myocardial infarction (5); dementia (4); epilepsy (4); lupus nephritis (4); preeclampsia (4); Q fever (4); transient ischemic attack (4); viral infections (4); cerebral infarction (3); Chorea (3); Cognitive impairment (3); head and neck squamous cell carcinoma (3); ischemic stroke (3); lipid metabolism disorders (3); nonalcoholic steatohepatitis (3); periodontitis (3); pulmonary embolism (3); acute myocardial infarction (2); anticoagulant (2); cardiomyopathy (2).
A further 123 diseases each share a sentence with ACLY in 2 papers or fewer.